AMN1 (antagonist of mitotic exit network 1 homolog)
Tractability: PROTAC: ubiquitination databases record sites on it; its protein half-life has been measured.
Gene: Protein-coding gene on chromosome 12 (31,671,142 to 31,729,121, reverse strand). Ensembl gene ENSG00000151743.
Subcellular location (Human Protein Atlas): Centrosome
Gene Ontology:
Cellular component: microvillus membrane
Genetic constraint (gnomAD): Loss-of-function variants: 14 observed, 26.13 expected, observed/expected ratio (o/e) 0.54, 90% interval 0.35 to 0.84. The upper end of that interval is the gene's LOEUF score, 0.84, which puts it in group 3 of 6, group 1 being the genes least tolerant of losing a copy. Missense variants: 202 observed, 273.63 expected, observed/expected ratio (o/e) 0.74, 90% interval 0.66 to 0.83. Synonymous variants: 101 observed, 100.15 expected, observed/expected ratio (o/e) 1.01, 90% interval 0.86 to 1.19.
Homologues: Orthologues: chimpanzee AMN1 (99% identical), macaque AMN1 (99% identical), dog AMN1 (91% identical), guinea pig AMN1 (89% identical), pig AMN1 (82% identical), rabbit AMN1 (80% identical), rat Amn1 (80% identical), mouse Amn1 (76% identical), tropical clawed frog amn1 (58% identical), zebrafish amn1 (45% identical).
Diseases named in the same sentence as AMN1 in open-access papers:
AMN1 is named in the same sentence as 3 diseases in open-access papers, as found by Europe PMC text mining. Sharing a sentence is not in itself a finding about the gene and the disease. The quoted sentences say what the papers report.
osteosarcoma (1 paper, 2020). A usually aggressive malignant bone-forming mesenchymal neoplasm, predominantly affecting adolescents and young adults. "Although there are no relative studies about the role of ZP3 in osteosarcoma, even if in cancer, combined with the findings of our study, we should also pay attention to AMN1 and ZP3 in osteosarcoma in a certain extent." (PMID 33195283, 2020). "Furthermore, AMN1 and ZP3 may be protective factors in osteosarcoma (HR: 1.26e−36 and 1.13e−07, respectively), whereas LIMS1, SAMD4A, and SPARC appear to be harmful factors in this setting (HR: 699.2, 167, and 298.7, respectively)." (PMID 33195283, 2020).
cancer (2 papers, 2009 to 2020). A tumor composed of atypical neoplastic, often pleomorphic cells that invade other tissues. "Among the 21 validated genes, the strikingly decreased transcription of PTPRG and AMN1 and increased transcription of UPP1 potentially support data on cell cycle disturbances relevant to cancer, stem cell and neurodegenerative diseases' research." (PMID 19763259, 2009). "TERA and AMN1 can be connected to neural stem cells through several types of cancer, neural differentiation (in the case of TERA) and through the role of monocilia for neurogenesis (in the case of AMN1)." (PMID 19763259, 2009). "All in all, we have demonstrated that AMN1 and TERA are genes of basically unknown function that are worthy of further investigation to understand their roles in neurogenesis, cancer and γ-secretase biology." (PMID 19763259, 2009).
AMN1 also shares sentences with these, for which no sentence is quoted: neurodegenerative disease (1 paper).